TIMP1 (TIMP metallopeptidase inhibitor 1)
Diseases named in the same sentence as TIMP1 in open-access papers (continued):
Sharing a sentence is not in itself a finding about the gene and the disease.
liver fibrosis (continued). "Downregulation of PAI-1 ameliorates hepatic fibrosis by facilitating matrix degradation through upregulation of MMPs and downregulation of TIMP-1." (PMID 36059948, 2022). "This was supported by Sri Ningsih, who revealed that the administration of gambir extract decreased TIMP-1 and collagen I expression, which then suppressed the development of liver fibrosis." (PMID 35795272, 2022). "Detection of the mRNA levels of a series of liver fibrosis-related molecules: Acta2, Col1a1, Tgfb1, and Timp1 in livers from IL-21−/−p40−/−IL-2Ra−/− mice and controls suggested no significant change of liver fibrosis." (PMID 35300072, 2022). "The results revealed the reduced production of extracellular collagen by adjusting the balance of matrix metalloproteinase (MMP) 2, MMP9, and tissue inhibitor of matrix metalloproteinase 1 (TIMP1) in PZH-treated CCl4-induced liver fibrosis." (PMID 36188553, 2022). "TIMP-1 has been identified as a marker for liver fibrosis as a result, and its presence implies an increase in liver damage." (PMID 36080111, 2022). "The assessment of TIMP-1 and other direct markers of fibrosis in serum, which has been validated as the enhanced liver fibrosis (ELF) test, is used in patients with non-alcoholic fatty liver disease (NAFLD)." (PMID 35625637, 2022). "Serum PIIINP, TIMP-1, and HA are combined to calculate the Enhanced Liver Fibrosis (ELF) score, initially developed from a chronic liver disease cohort." (PMID 36523781, 2022). "Among the factors that indicate the prevalence and spread of liver fibrosis is the tissue inhibitor of matrix metalloproteinases-1 (TIMP-1)." (PMID 36110559, 2022). "The level of fibrosis‐related genes (Acta2, Col1a1 and Timp1) was increased in liver injury groups for 10 weeks compared to 4 and 6 weeks, which confirmed the extent of liver fibrosis evaluated by fibrosis score." (PMID 33410581, 2021). "Recently, the enhanced liver fibrosis (ELF) test combined with HA, PIIINP, and TIMP-1, which revealed a similar diagnostic accuracy to the histological examinations in fibrosis progression evaluation in ALD patients." (PMID 34068269, 2021). "Our results exhibited that crude extract and its carotenoid enrich fractions play a dual role in liver fibrosis as preserved the balance between MMP9/TIMP1 ameliorating liver fibrosis." (PMID 33628797, 2021). "The imbalance in the ECM in the liver leads to liver fibrosis, TIMP1 is a key enzyme that regulates ECM metabolism, and HSCs are the main source of these proteins in the liver." (PMID 34833975, 2021). "Previous study reported that catalase, anti-IL-6, or siRNA-IL-6 inhibited the phosphorylation of p38 in Kupffer cells which co-cultured hepatic stellate cell and also blocked TIMP1 upregulation and collagen I accumulation for liver fibrosis." (PMID 33809062, 2021). "The serum level of TIMPs was suggested as an indicator of hepatic fibrosis: increased serum levels of TIMP-1 in chronic hepatitis C patients correlated with the stage of liver fibrosis, better than those of TIMP-2." (PMID 34065048, 2021). "They investigated the therapeutic effect of TIMP-1-silencing MSCs in a rat model of CCl4-induced liver fibrosis when transplanted intravenously." (PMID 34200425, 2021). "Another study showed that PTEN-deficient mice develop progressive liver fibrosis characterised by the increased expression of ACTA2, COL1 and tissue inhibitor of matrix metalloproteinase (TIMP)-1." (PMID 34648138, 2021). "Development of liver fibrosis was accompanied by significant increases in circulating tissue inhibitor of metalloproteinase 1 (TIMP1) and ECM remodeling markers of pericellular fibrosis, PRO-C4 and C6M." (PMID 34944770, 2021).
liver fibrosis (continued). "TIMP1 has been shown to be elevated in adult populations with hepatic fibrosis due to chronic hepatitis C, Alcoholic Liver Disease, and NAFLD, and in children with liver disease secondary to cystic fibrosis." (PMID 32150543, 2020). "The mRNA levels of collagen type 1 (Col1a1), connective tissue growth factor (CTGF), and tissue inhibitor of matrix metalloproteinase 1 (Timp1), which are indicators of liver fibrosis, were measured." (PMID 32316419, 2020). "MMP2 and TIMP1, as representative cytokines to study the process of liver fibrosis, can participate in the progress of liver fibrosis." (PMID 32463570, 2020). "In patients with HCV, TIMP-1 serum protein and mRNA levels are positively correlated with the staging of liver fibrosis." (PMID 32664553, 2020). "MMP-2 suppresses collagen I expression, and the loss of MMP-2 aggravates fibrosis, suggesting that MMP-2 suppresses TIMP-1 upregulation during liver fibrosis." (PMID 32664553, 2020). "TIMP1 has been reported to be upregulated in serum and liver during the progression of hepatic fibrosis in human as well as animal models." (PMID 33315911, 2020). "In animal models, it has been reported that treatment with metformin protects against hepatic fibrosis by decreasing the expression of profibrogenic biomarkers such as TIMP-1." (PMID 30769840, 2019). "Similar to the CCl4-induced fibrosis model, Med23 silencing also resulted in increasing mRNAs related to liver fibrosis, including Col1a1, Col3a1, Tgfβ1, Pdgfβ, Tgfβr1, Pdgfrβ, and Timp1." (PMID 31805036, 2019). "Reduction of liver fibrosis corroborates the results obtained by measurement of hepatic pro-fibrotic (TIMP-1, TGF-β1) and anti-fibrotic factors (MMP-9)." (PMID 31015492, 2019). "The ratio of matrix metalloproteinase-2 (MMP2) and its inhibitor TIMP2 has been found to be imbalanced in hepatic fibrosis whereas MMP-9/TIMP-1 ratio is dysregulated in liver metastasis." (PMID 30087389, 2018). "MMP-1/TIMP-1 ratio is useful for the diagnosis of hepatic fibrosis and correlates with degree of portal inflammation." (PMID 29255622, 2018). "ALDH2 deficiency accentuated CCl4‐induced liver fibrosis in mice, accompanied by increased expression of collagen 1α1, α‐SMA and TIMP‐1." (PMID 29799157, 2018). "Hepatic TIMP-1 expression was upregulated following induction of liver fibrosis by bile duct ligation (BDL) or by carbon tetrachloride (CCl4)." (PMID 28386095, 2017). "Here, we study the functional relevance of TIMP-1 in the development of liver fibrosis and hepatocellular carcinoma in vivo." (PMID 28386095, 2017). "Previous studies have shown that PNS inhibit hepatic stellate cell activation and liver fibrosis via downregulating TIMP-1, PC-I, PC-III and TGF-β1 expressions." (PMID 28106137, 2017). "Meanwhile, the mRNA expression levels of Acta2, MMP13, Coll1a1, and TIMP1 were examined, which are all classical profibrogenic markers during liver fibrosis process." (PMID 29464186, 2017). "For instance, one study in CHC patients demonstrated the association between serum TIMP-1 and the METAVIR hepatic fibrosis score in pretreatment biopsies." (PMID 28827788, 2017). "In line with the hepatic fibrogenesis in HFrD-fed A/AHep mice, there was strongly increased expression of liver fibrosis marker genes (Col1A1, Col3A1, Timp1 and Pdgfr-β) in the livers of the HFrD-fed A/AHep mice." (PMID 28781602, 2017). "The mRNA markers for hepatic fibrosis (Col1a1 and Timp1 mRNA) showed a pattern similar to that of hepatic TG." (PMID 28159867, 2017). "TIMP-1 expression is upregulated in chronic liver injury and liver fibrosis, two conditions that precede the development of hepatocellular carcinoma (HCC)." (PMID 28386095, 2017). "Time course studies further revealed a strong association (r2 ≥ 0.52) between plasma markers of inflammation (TLR2 activators) and hepatic fibrosis markers (Col1A, Timp1, LoxL2)." (PMID 26761430, 2016).
liver fibrosis (continued). "TIMP-1 is also a contributory factor in the development of hepatic fibrosis as shown in animal models and patients." (PMID 27247426, 2016). "Another study reports that transplantation of stem cells expressing TIMP-1-shRNA is able to inhibit the progression of liver fibrosis and possibly restore the liver function in a rat model." (PMID 27247426, 2016). "The excessive accumulation of extracellular matrix of hepatic fibrosis is positively correlated with tissue inhibitors of metalloproteinase 1 (TIMP1)." (PMID 27175276, 2016). "The enhanced liver fibrosis score, which is a serum-based test of hyaluronic acid, TIMP-1, and propeptide of type III procollagen, has been shown to predict transplant-free survival in PSC40." (PMID 27347393, 2016). "ROS can induce tissue injury via lipid peroxidation, and enhance liver fibrosis by increasing tissue inhibitors of metalloproteinases (TIMP-1), which leads to an increase in collagen synthesis and accumulation." (PMID 26062544, 2015). "In one study, β-caryophyllene exhibited high scavenging activity against hydroxyl radicals and superoxide anions, which inhibited lipid peroxidation and suppressed expression of Col1a1 and TIMP-1 in CCl4-induced mouse liver fibrosis." (PMID 25897319, 2015). "FZHY tablet exhibits antifibrotic activity by inducing apoptosis in HSC-T6 cells through p38 and SAPK/JNK pathways, and inhibits liver fibrosis through decreasing transcription of TIMP-1, PDGF-B, and PDGF receptor β1 in vivo." (PMID 25897319, 2015). "In animal models, the serum level of TIMP-1 correlates with dexamethasone-induced liver fibrosis in rats." (PMID 25549087, 2014). "Our results showed that astaxanthin ameliorated liver fibrosis partly by preserving the balance between MMP2/TIMP1." (PMID 24860243, 2014). "The accumulation of hydroxyproline and collagen fibers was found in the CCl4 group, whereas ginseng extract and ginsenoside Rb1 decreased hepatic hydroxyproline and TIMP-1 levels to inhibit liver fibrosis." (PMID 25344394, 2014). "Panax ginseng extract and ginsenoside Rb1 attenuate plasma aminotransferase activities and liver inflammation to inhibit CCl4-induced liver fibrosis through down-regulation of hepatic prostaglandin E2 and TIMP-1." (PMID 25344394, 2014). "Tissue inhibitor of metalloproteinase (TIMP)-1, the most important endogenous inhibitor of most MMPs, plays a crucial role in the pathogenesis of liver fibrosis, and its expression in HSCs is enhanced by TNF-α." (PMID 23755201, 2013). "Inversely, transgenic mice overexpressing TIMP-1 in the liver show increased liver fibrosis after CCl4 treatment, whereas TIMP-1 overexpression alone does not result in liver fibrosis." (PMID 23755201, 2013). "Expressions of both TIMP-1 and -2 were found to be elevated in human and rat models of liver fibrosis." (PMID 23829789, 2013). "In contrast to our results, it has been reported that CCl4-induced liver fibrosis and liver injury are increased in TIMP-1−/− mice." (PMID 23755201, 2013). "To elucidate the mechanisms by which TNF-α contributes to BDL-mediated liver fibrosis, we focused on TIMP-1, which is an endogenous inhibitor of MMPs." (PMID 23755201, 2013). "In conclusion, we observed that TNF-α produced by cholestasis promoted liver fibrosis via TIMP-1 production from HSCs." (PMID 23755201, 2013). "Tissue inhibitor of metalloproteinase (TIMP)-1 plays a crucial role in the pathogenesis of liver fibrosis." (PMID 23755201, 2013). "Reduced liver fibrosis in CCL3−/− mice was associated with altered expression of Col1a1, TIMP1, and MMP9 (P<0.05)." (PMID 23799074, 2013). "Based on our results, we suggest that BCAA improves liver fibrosis by downregulating Smad-4, TIMP-1, and Col1α2 through the inhibition of TGF-β1." (PMID 24223741, 2013). "The results, which indicate that TNF-α increases liver fibrosis through TIMP-1 production from HSCs, suggest novel therapeutic possibilities for treating liver fibrosis." (PMID 23755201, 2013).
liver fibrosis (continued). "In patients with chronic HCV infection, TIMP-1 mRNA levels correlate with the grade of liver fibrosis and HCV itself is able to stimulate TIMP-1 mRNA expression." (PMID 23516586, 2013). "Our study also provided clues that based on the changes following PZQ treatment, the levels of TGF-β and TIMP-1 were potential biomarkers for regression of liver fibrosis." (PMID 21629648, 2011). "TIMP-1 plays an important role in protecting against acute and chronic liver injury and subsequently inhibiting liver fibrosis induced by CCl4." (PMID 21711826, 2011). "TIMP-1 has been suggested to be a serum marker for liver fibrosis, and the expression is induced during liver injury." (PMID 21711826, 2011). "It is well established that activation of HSCs is a key event in the pathophysiology of hepatic fibrosis and is accompanied by induction of TIMP-1." (PMID 21711826, 2011). "TIMP-1 knockout mice also displayed greater degree of liver fibrosis after chronic CCl4 injection when compared with wild-type mice." (PMID 21711826, 2011). "This first pediatric study suggests that TIMP-1 is clinically useful for predicting liver fibrosis in HCV patients." (PMID 21858035, 2011). "TIMP-1 has been suggested as a profibrogenic factor to promote liver fibrosis as liver-specific TIMP-1 transgenic mice were resistant to fibrosis resolution and TIMP-1 neutralizing antibody inhibited liver fibrosis." (PMID 21711826, 2011). "The final effect of TIMP-1 on liver fibrosis is determined by the balance between these stimulatory and inhibitory effects." (PMID 21711826, 2011). "TIMP-1 plays dual roles in regulating liver fibrosis by inhibiting liver fibrosis via protecting against liver injury or by promoting liver fibrosis via protecting against HSC death." (PMID 21711826, 2011). "Surprisingly, the grade of liver fibrosis was higher in TIMP-1-/- mice with predominant bridging in morphology than that in wild-type mice, which was determined by Sirius red staining for collagen." (PMID 21711826, 2011). "In contrast, these TIMP1 knockout mice had an exacerbated acute liver fibrosis." (PMID 39970910, 2025). "Similarly, the levels of mRNA related to liver fibrosis (Col1A1, Acta2, Timp1, and Tgfb1) were significantly increased in the DM group, which were significantly reduced by the LFD treatment." (PMID 41374037, 2025). "Matrix metalloproteinases (MMPs) are capable of degrading the ECM, whereas tissue inhibitor of metalloproteinases-1 (TIMP-1) is significantly upregulated during DMN-induced liver fibrosis, inhibiting the activity of MMPs and promoting the deposition of the ECM." (PMID 39859410, 2025). "The important regulatory effect of the TIMP1, being expressed in the liver endothelial and stellate cell populations, on the formation and degradation of liver fibrosis was observed, as well as its participation in ventricular remodeling caused by hypertension, leading to myocardial fibrosis." (PMID 41153660, 2025). "In addition, collagen, type 1, alpha 1 (Col1α1) and tissue inhibitor of metalloproteinase 1 (Timp1), markers of liver fibrosis, were also significantly upregulated in the FXRhep−/− mice, suggesting increased fibrosis." (PMID 40377496, 2025). "Furthermore, in our observations, MSC-CM was found to elevate the expression of MMP1, thereby promoting enhanced ECM degradation and rectifying the MMP1/TIMP1 imbalance, ultimately supporting liver fibrosis resolution." (PMID 38874773, 2024). "Moreover, probiotic bacteria hindered the induction of hepatic fibrosis by downregulating the expressions of tissue inhibitors of metalloproteinase-1 (TIMP-1) and α-smooth muscle actin (α-SMA)." (PMID 38338453, 2024). "Gallic acid exhibited the ability to inhibit HSCs cell proliferation in a dose-dependent and time-dependent manner, decrease α-SMA expression, lower the levels of liver injury markers such as PCNA, PDGF-BB, TIMP-1, HP, and reduce collagen deposition in a rat model of liver fibrosis." (PMID 39185304, 2024).
liver fibrosis (continued). "Suppressing TIMP1 can alleviate hepatic fibrosis and myocardial fibrosis." (PMID 37266443, 2023). "The altered inhibition by TIMP1 of the activity of MMP-9 promotes liver fibrosis." (PMID 38001866, 2023). "The role of TIMP-1 in the development of liver fibrosis has been widely reported." (PMID 36816804, 2023). "The more serious the hepatic fibrosis is, the higher the level of TIMP-1 gene expression." (PMID 36569295, 2022). "The mRNA levels of liver fibrosis markers (Acta2, Col1a1, Col3a1, and Timp1), cholangiocyte proliferation markers (Krt7 and Krt19), inflammation markers (Il6 and Il1b), and the progenitor cell marker (Sox9) were markedly decreased in miR-200c-BDL mice compared to con-BDL mice." (PMID 34880414, 2022). "The global cytokine surveys of HSC-CM have demonstrated that TNF-α, agrin, PDGF, activin A, GM-CSF, IFN-γ, IL-1β, IL-4, IL-6, IL-10, IL-13, and TIMP-1, which subsequently induce acute inflammation and liver fibrosis, were elevated in aHSC-CM relative to the qHSC-CM." (PMID 36142683, 2022). "This phenomenon could be a key element explaining the slowness of fibrosis reversion, especially since it has been shown that treatment based on anti-TIMP1 antibodies leads to an improvement in hepatic fibrosis induced by CCl4 in rodents." (PMID 35057565, 2022). "TIMP-1 is overexpressed in liver tissues during hepatic fibrogenesis, which is consistent with our findings, and its expression is directly related to the stage of hepatic fibrosis." (PMID 36080111, 2022). "With the progression of liver fibrosis, the content of TIMP1 in liver increases." (PMID 36152060, 2022). "Furthermore, the tissue inhibitor of metalloproteinases 1 (TIMP-1) also controls the alteration of the extracellular matrix in hepatic fibrosis via MMPs." (PMID 36014565, 2022). "The higher quantities of COL1A1, Lama1, and Timp1 proteins were expressed in the model group, which were considerably subdued by PC administration, signifying that PC reduced CCl4-induced liver fibrosis." (PMID 35721129, 2022). "Besides, the hepatic expressions of TIMP1 and TGFβ that related to hepatic fibrosis were induced by a high-fat diet in TRIM67 WT mice but not in TRIM67 KO mice." (PMID 35806477, 2022). "Moreover, the mRNA expression of hepatic fibrosis markers, such as Col1a1 and Timp1, was significantly increased in CCl4-induced rats and repressed by Qijia Rougan decoction treatment." (PMID 35846987, 2022). "Gambir and green tea are believed to suppress the expression of inflammatory cytokines and profibrotic mediators, such as TIMP-1 and collagen I. This was proved by Sri Ningsih in their study on the role of gambir extract in suppressing the development of liver fibrosis." (PMID 35795272, 2022). "Therefore, because TIMP-1 expression is mostly correlated with the level of hepatic fibrosis, it was enhanced in liver tissues and serum during hepatic fibrogenesis in liver-diseased individuals and experimental animal models of hepatic fibrogenesis." (PMID 36080111, 2022). "They indicated that transplantation of MSCs expressing TIMP-1-shRNA could inhibit the progression of liver fibrosis and possibly restore the liver function." (PMID 34200425, 2021). "Moreover, TIMP1 is one of three parameters in the Enhanced Liver Fibrosis (ELF) test, a non-invasive biomarker score to predict advanced fibrosis in patients with NAFLD." (PMID 33435509, 2021). "We also investigated the levels of α1 type 1 collagen (Col1α1), a factor associated with collagen fiber degradation, liver fibrosis‐related genes such as matrix metallopeptidase‐2 (MMP‐2) and tissue inhibitor of metalloproteinase‐1 (TIMP1), an inhibitor of MMP." (PMID 34532001, 2021).